BHLHE41 (basic helix-loop-helix family member e41)
Description:
Transcriptional repressor involved in the regulation of the circadian rhythm by negatively regulating the activity of the clock genes and clock-controlled genes. Acts as the negative limb of a novel autoregulatory feedback loop (DEC loop) which differs from the one formed by the PER and CRY transcriptional repressors (PER/CRY loop). Both these loops are interlocked as it represses the expression of PER1 and in turn is repressed by PER1/2 and CRY1/2. Represses the activity of the circadian transcriptional activator: CLOCK-BMAL1 heterodimer by competing for the binding to E-box elements (5'-CACGTG-3') found within the promoters of its target genes. Negatively regulates its own expression and the expression of DBP and BHLHE41/DEC2. Acts as a corepressor of RXR and the RXR-LXR heterodimers and represses the ligand-induced RXRA/B/G, NR1H3/LXRA, NR1H4 and VDR transactivation activity. Inhibits HNF1A-mediated transactivation of CYP1A2, CYP2E1 AND CYP3A11 (By similarity).
Synonyms: bHLHb3; hDEC2; SHARP-1; DEC2; SHARP1; FNSS1
Tractability: PROTAC: UniProt records ubiquitination sites on it; ubiquitination databases record sites on it.
Gene: Protein-coding gene on chromosome 12 (26,120,030 to 26,125,037, reverse strand). Ensembl gene ENSG00000123095.
Subcellular location: Nucleus
Subcellular location (Human Protein Atlas): Nucleoplasm; Vesicles
Pathways (Reactome):
Circadian clock: BMAL1:CLOCK,NPAS2 activates circadian expression
Gene Ontology:
Molecular function: bHLH transcription factor binding; DNA-binding transcription repressor activity, RNA polymerase II-specific; E-box binding; protein binding; protein heterodimerization activity; sequence-specific double-stranded DNA binding; DNA-binding transcription factor activity, RNA polymerase II-specific; histone deacetylase binding; MRF binding; RNA polymerase II cis-regulatory region sequence-specific DNA binding; RNA polymerase II-specific DNA-binding transcription factor binding; DNA binding; protein dimerization activity; protein homodimerization activity
Biological process: negative regulation of transcription by RNA polymerase II; anterior/posterior pattern specification; circadian regulation of gene expression; negative regulation of DNA-templated transcription; negative regulation of myotube differentiation; regulation of neurogenesis; circadian rhythm; regulation of DNA-templated transcription
Cellular component: chromatin; nucleus
Genetic constraint (gnomAD): Loss-of-function variants: 15 observed, 18.95 expected, observed/expected ratio (o/e) 0.79, 90% interval 0.53 to 1.22. The synonymous counts are far from expectation, so gnomAD's model fits this gene poorly and the ratio says little. Missense variants: 630 observed, 495.01 expected, observed/expected ratio (o/e) 1.27, 90% interval 1.19 to 1.36. Synonymous variants: 371 observed, 250.89 expected, observed/expected ratio (o/e) 1.48, 90% interval 1.36 to 1.61.
Homologues: Orthologues: chimpanzee BHLHE41 (100% identical), macaque BHLHE41 (96% identical), dog BHLHE41 (96% identical), pig BHLHE41 (96% identical), mouse Bhlhe41 (68% identical), rat Bhlhe41 (68% identical), tropical clawed frog bhlhe41 (56% identical), zebrafish bhlhe41 (50% identical), Drosophila melanogaster cwo (12% identical), Drosophila melanogaster E(spl)mgamma-HLH (11% identical), Drosophila melanogaster E(spl)mbeta-HLH (10% identical), Drosophila melanogaster Hesr (10% identical), and 5 more. Paralogues in human: BHLHE40 (37% identical), HEY2 (16% identical), HEY1 (14% identical), HEYL (13% identical), HES1 (13% identical), HES6 (13% identical), HES4 (11% identical), HELT (11% identical), HES7 (10% identical), HES5 (10% identical), HES3 (9% identical), HES2 (9% identical).
Diseases named in the same sentence as BHLHE41 in open-access papers:
BHLHE41 is named in the same sentence as 84 diseases in open-access papers, as found by Europe PMC text mining. Sharing a sentence is not in itself a finding about the gene and the disease. The quoted sentences say what the papers report.
breast carcinoma (25 papers, 2012 to 2026). "In this study, we aimed to explore the mechanism by which BHLHE41 regulates the invasion of breast cancer cells." (PMID 32073238, 2020). "In breast cancer, an increase in BHLHE41 also inhibited metastasis and proliferation." (PMID 31936274, 2020). "Our results indicate that BHLHE41 may play a similar role in regulating cell invasion in breast cancers, but the exact pathway may be different according to different molecular subtypes." (PMID 32073238, 2020). "Therefore, BHLHE41 is recognized as a tumor suppressor gene in breast cancer." (PMID 39590319, 2024). "Thus, to conclude, BHLHE41 suppresses invasion of breast cancer cells, but the detailed regulatory pathways may be different according to different cell types." (PMID 32073238, 2020). "Furthermore, BHLHE41 was independently discovered as a metastasis suppressor gene in breast cancer." (PMID 22530051, 2012). "Currently, the potential impact of alterations in BHLHE41 expression levels on PGK1 expression and subsequent breast cancer progression remains an area that necessitates further investigation and validation." (PMID 39590319, 2024). "In vivo validation using immunohistochemistry on clinical samples from 10 breast cancer patients with ovarian metastases confirmed that GPR183, BHLHE41, and CD83 were highly expressed in tumor tissues, while SLC25A37 and SELL were highly expressed in adjacent normal tissues." (PMID 42101520, 2026). "Concurrently, BHLHE41 modulates cancer progression through competitive binding at promoter regions of EMT master regulators (Snail, Slug, and Twist), thereby facilitating EMT-driven breast cancer cell invasion and metastasis." (PMID 40508038, 2025). "A crucial molecular determinant of the malignant behaviour of breast cancer, and in particular of the metastasizing capacity, is the p63 transcriptional target gene SHARP1 (known also as DEC2 or BHLHE41) that, in triple breast cancer, results in a very negative prognostic fate." (PMID 35201443, 2021). "In our study, it was discovered that BHLHE41 overexpression largely enhanced the levels of BHLHE41 and E-cadherin but repressed the levels of HIF-1α, N-cadherin, vimentin, and MMP9 in hypoxia-induced CC cells, which was consistent with the report of BHLHE41 in breast cancer." (PMID 35615737, 2022).
triple-negative breast carcinoma (9 papers, 2014 to 2023). An invasive breast carcinoma which is negative for expression of estrogen receptor (ER), progesterone receptor (PR), and human epidermal growth factor receptor 2 (HER2). "A study proved that BHLHE41 was a key regulator of invasive and metastatic phenotypes in triple-negative breast cancer, and it can bind to HIF to promote the HIF protease degradation." (PMID 35615737, 2022). "BHLHE41 has been shown to suppress the metastasis of aggressive triple-negative breast cancers through the degradation of hypoxia inducing factor HIF that promotes tumor angiogenesis." (PMID 31819067, 2019).
endometrial cancer (7 papers, 2014 to 2023). Primary or metastatic malignant neoplasm involving the endometrium (mucous membrane that lines the endometrial cavity). "Comparison of the mRNA levels of BHLHE41/DEC2 between 20 normal endometrial tissue specimens (NEM) and 37 primary huma endometrial cancer (HEC) specimens showed that HEC had a significantly higher expression of BHLHE41/DEC2." (PMID 37511489, 2023). "In endometrial cancer, BHLHE41 expression is downregulated, and overexpressed BHLHE41 reduces HIF-1 levels thereby attenuating endometrial cancer angiogenesis." (PMID 35615737, 2022). "Another report indicated that overexpression of BHLHE41 in endometrial cancer Ishikawa and HEC-1B cells inhibited cell migration, invasion, and metastasis by attenuating NOTCH1 signaling." (PMID 31487856, 2019).
osteosarcoma (7 papers, 2015 to 2024). A usually aggressive malignant bone-forming mesenchymal neoplasm, predominantly affecting adolescents and young adults. "Notably, they also identified a positive correlation between BHLHE41 expression and poor prognosis in osteosarcoma patients." (PMID 39590319, 2024).
depression (6 papers, 2015 to 2025). "Supporting these observations, the genes Nr1d1 and Bhlhe41, which have been associated with the control of circadian rhythm function and depression, were downregulated in the PFC of transgenic mice." (PMID 33795014, 2021). "Overall, BHLHE41, EPCAM, and GSTM2 consistently suggested their potential as reliable mechanism-associated genes for Depression and BC, with AUC values exceeding 0.7 across both training and validation datasets." (PMID 40508038, 2025). "Although previous studies have reported associations between BHLHE41/GSTM2 and both depression and BC, this research is the first to focus on their regulatory roles through the immune system and MAPK pathway." (PMID 40508038, 2025). "The literature mining analysis revealed that BHLHE41 and GSTM2 have been previously implicated in both Depression and BC pathogenesis, while EPCAM has been primarily associated with BC." (PMID 40508038, 2025). "Least absolute shrinkage and selection operator (LASSO) regression identified five candidate genes (BHLHE41, EPCAM, ADH4, GSTM2, GADD45G) from the Depression and BC datasets." (PMID 40508038, 2025).
gastric cancer (5 papers, 2019 to 2024). A primary or metastatic malignant neoplasm involving the stomach. "In gastric cancer (GC), BHLHE41 expression was downregulated in GC tissues, and lower expression was associated with higher TNM stage and worse overall survival of GC patients." (PMID 38811952, 2024). "Li et al6 pointed out that BHLHE41 suppressed tumour proliferation and metastasis by regulating ERK/NF‐kappaB pathway in gastric cancer." (PMID 32073238, 2020). "A negative correlation between the expression level of BHLHE41 and tumor invasion, lymph node metastases, TNM stage, and poor survival, was found among patients with gastric cancer." (PMID 31936274, 2020).
pancreatic cancer (5 papers, 2016 to 2023). "Suppression of EMT and metastasis by BHLHE41 has been observed in breast, endometrial, and pancreatic cancer." (PMID 34046336, 2021). "In human pancreatic cancer BxPC-3 cells, the knockdown of BHLHE41/DEC2 increased the nuclear expression of an EMT transcription factor, SNAI2, in the presence of TGF-β." (PMID 37511489, 2023). "In addition, BHLHE41 disrupts the epithelial–mesenchymal transition (EMT) in human endometrial and pancreatic cancer." (PMID 31936274, 2020).
thyroid cancer (4 papers, 2018 to 2024). "BHLHE41/DEC2 also suppresses the growth of thyroid cancer cell lines and their expression of HIF-1α." (PMID 37511489, 2023). "In thyroid cancer cell lines, overexpression of BHLHE41 downregulated HIF-1α protein and mRNA levels and obviously repressed cell migration and invasion, revealing that BHLHE41 may play a tumor suppressor effect in thyroid cancer by modulating the HIF-1α pathway." (PMID 35615737, 2022).
diabetes (3 papers, 2018 to 2024). "We additionally investigated the up- and downstream regulatory mechanisms associated with the upregulation of Bhlhe41 expression in diabetes." (PMID 39375536, 2024). "In this study, pySCENIC analysis of hippocampal neurons in scRNA-seq data revealed that Bhlhe41 upregulation was involved in the pathogenesis of diabetes-associated cognitive." (PMID 39375536, 2024). "To further clarify the mechanism underlying Bhlhe41-induced cognitive impairment in diabetes, we selected differentially expressed genes in hippocampal neurons scRNA-seq dataset for KOBAS analysis." (PMID 39375536, 2024). "This modulation of Bmal1 function through O-GlcNAcylation of Bmal1 at S424 links glucose and Bhlhe41 upregulation in hippocampal neurons, implicating Bmal1 as a potential therapeutic target for the treatment of cognitive impairment in diabetes." (PMID 39375536, 2024). "Based upon previous and present findings, we suggested that aberrant Bhlhe41 expression not only disrupted circadian rhythms but also induced cognitive impairment in diabetes." (PMID 39375536, 2024). "BHLHE41 also has a role in immune function and in addition toCAMK1D,AGER is implicated in diabetes along with the narcolepsy-related gene,HLA-DQB1." (PMID 34745571, 2020). "Among these are genes associated with insulin (MAX, NUCKS1, PIK3R1, PTPN11), diabetes (PIK3R1) and circadian-related processes (HNRNPU, BHLHE41)." (PMID 34745571, 2020). "Such treatment led to a decrease in binding of Clock to Bmal1 and a downregulation of Bhlhe41 and Dnajb4 expression, resulting in NCLX upregulation and an improvement in mitochondrial calcium overload, hippocampal neuron dysfunction, and cognitive impairment in diabetes." (PMID 39375536, 2024).
leukemia (3 papers, 2018 to 2023). A malignant (clonal) hematologic disorder, involving hematopoietic stem cells and characterized by the presence of primitive or atypical myeloid or lymphoid cells in the bone marrow and the blood. "MLL-AF6-expressing hematopoietic stem cells derived from mice with a genetic deletion of Bhlhe41/Dec2 delay leukemia development and decrease the potential for leukemia initiation." (PMID 37511489, 2023). "Mechanistically, BHLHE41/DEC2 binding sites in MLL-AF6 leukemia cells were enriched with H3K4me3 and H3K27ac transcriptionally active markers across the genome and activates genes related to the cell cycle, TGF-β signaling, FoxO signaling, HIF-1 signaling, and cancer." (PMID 37511489, 2023).
lung adenocarcinoma (3 papers, 2021 to 2023). A carcinoma that arises from the lung and is characterized by the presence of malignant glandular epithelial cells. "BHLHE41/DEC2 expression is associated with better prognosis in patients with lung adenocarcinoma (LUAD)." (PMID 37511489, 2023). "BHLHE41 expression was higher in normal lung than in lung adenocarcinoma (LUAD) tissues and was associated with better prognosis for the overall survival (OS) of patients." (PMID 34768959, 2021).
lung carcinoma (3 papers, 2014 to 2023). "To determine whether BHLHE41 protein expression is associated with the prognosis of patients with lung cancer, we performed IHC analysis of clinical specimens from 177 lung cancer cases." (PMID 34768959, 2021). "Taken together, these data suggest that BHLHE41 plays an important role in inducing autophagic cell death during early lung cancer cells and likely suppresses lung cancer progression." (PMID 34768959, 2021). "This study investigates the role of BHLHE41 in lung cancer progression." (PMID 34768959, 2021). "BHLHE41 also has been reported to act as a tumor suppressor gene in the lung, however, the roles of BHLHE41 in lung cancer development remain unclear." (PMID 34768959, 2021). "First, to determine whether BHLHE41 expression is related to the outcome of patients with lung cancer, we performed a Kaplan–Meier analysis of overall survival (OS) using The Cancer Genome Atlas (TCGA) data." (PMID 34768959, 2021). "Our results showed an increased number of autophagosomes which are degraded following fusion with lysosomes, influenced by BHLHE41 expression and supported the hypothesis that autophagy is enhanced upon BHLHE41 induction in lung cancer cells." (PMID 34768959, 2021). "In the present study, we, therefore, examine the correlation between BHLHE41 expression and the prognosis of patients with NSCLC and explored the potential roles of BHLHE41 as a tumor suppressor during lung cancer development and progression." (PMID 34768959, 2021).
ovarian carcinoma (3 papers, 2019 to 2021). A malignant neoplasm originating from the surface ovarian epithelium. "However, of the four TFs (PITX1, RARA, FOXF1/A1, and BHLHE41/40) that matched the binding motifs in DEG promoters, only one, FOXA1, has previously been implicated in ovarian cancer specifically." (PMID 34215221, 2021). "Knockdown experiments showed that CPNE8 and BHLHE41—the former was CCC-predominant, and the latter was HGSC-predominant in PC1 by PCA—regulate the growth of ovarian cancer cells in a histotype-preferential manner." (PMID 31487856, 2019).
cardiac hypertrophy (2 papers, 2013 to 2021). "Bhlhe41 was shown to modulate hypertension susceptibility, Per1 was found to play a role in regulating blood pressure, Dbp functions in cardiac hypertrophy, ventricular function, and contractility, while Bhlhe40 functions in cardiac morphogenesis and development." (PMID 24255707, 2013).
colorectal cancer (2 papers, 2023 to 2025). A primary or metastatic malignant neoplasm that affects the colon or rectum. "Dysregulation of BHLHE41, a gene implicated in tumor progression, has been substantiated within the context of breast and colorectal cancers." (PMID 37314494, 2023).
Hypertension (2 papers, 2013 to 2020). The presence of chronic increased pressure in the systemic arterial system. "In contrast, gene expression profiling of Spontaneously Hypertensive (SHR) rats, a genetic model of hypertension, demonstrated decreased expression of Bmal1 and Npas2, while Per1, Per2, Per3, Cry1, Cry2, Bhlhe41 and Csnk1D were all upregulated compared to naïve WKY controls." (PMID 33127986, 2020).
kidney cancer (2 papers, 2020 to 2023). Primary or metastatic malignant neoplasm involving the kidney. "A significant increase in the expression of BHLHE41 in kidney cancer was observed in studies under the TCGA." (PMID 31936274, 2020). "Significant upregulation of BHLHE41 expression in kidney cancer was observed in TCGA analysis." (PMID 37443682, 2023).
narcolepsy (2 papers, 2014 to 2020). A sleep disorder characterized by a tendency for excessive sleepiness during the day which occurs even after adequate sleep in the nighttime. "Important genes and pathways that link PD, narcolepsy, and IR areCACNA1C, CAMK1D, BHLHE41, HMGB1, and AGE-RAGE." (PMID 34745571, 2020).
prostate carcinoma (2 papers, 2017 to 2023). A carcinoma that arises from epithelial cells of the prostate gland. "Such a hypothesis gains credence considering the observation that TGF-β induces the upregulation of BHLHE40 and the downregulation of BHLHE41 in prostate cancer cells (PC-3)." (PMID 38067152, 2023). "Thus, BHLHE41 has been shown to promote oncogenesis in renal and prostate cancer." (PMID 28715484, 2017).
renal carcinoma (2 papers, 2016 to 2019). A carcinoma arising from the epithelium of the renal parenchyma or the renal pelvis. "Overexpression or knockdown of BHLHE41 in renal cancer cell lines had no discernible phenotype with respect to cell proliferation, or migration, under either normoxic or hypoxic conditions." (PMID 27384883, 2016). "We knocked down the expression of BHLHE41 by siRNA in a number of renal cancer cell lines by transient transfection but did not observe a difference in growth rate or cell migration under either hypoxic or normoxic conditions." (PMID 27384883, 2016). "In addition, neither transient, nor stable overexpression of BHLHE41 in the renal cancer cell lines we tested, resulted in an observable phenotype." (PMID 27384883, 2016).
renal cell carcinoma (2 papers, 2018 to 2023). "In contrast, several studies support that BHLHE41/DEC2 has the functions in the development of renal cell cancer (RCC)." (PMID 37511489, 2023). "Although the oncogenic functions of BHLHE41/DEC2 and its relationship with HIF in RCC have not yet been completely elucidated, all reports indicate that BHLHE41/DEC2 is involved in the development and progression of renal cell cancer development." (PMID 37511489, 2023).
Arrhythmia (1 paper, 2025). Any cardiac rhythm other than the normal sinus rhythm. "Notably, the SAN_CM regulatory network also included the transcription factors BHLHE41 and RORA, regulators of the mammalian circadian clock, which were proposed to underlie time-of-day variation in arrhythmia susceptibility." (PMID 41162788, 2025).
asthma (1 paper, 2023). "Bhlhe41/Dec2-deficient mice lack the expression of interleukin 4 (IL-4), IL-5, IL-13, and IL-17 in vitro and in vivo in an asthma model and in response to a challenge with a parasite antigen." (PMID 37511489, 2023).